FBN1 (fibrillin 1)
Diseases named in the same sentence as FBN1 in open-access papers (continued):
Sharing a sentence is not in itself a finding about the gene and the disease.
Marfan syndrome (continued). "marfan syndrome (MFS) is a systemic, autosomal dominant disease of connective tissue cause by mutations in the gene encoding fibrillin-1, a major component of the microfibril network of the ECM." (PMID 26371162, 2015). "Mutations in FBN1 cause an autosomal dominant connective tissue disorder, Marfan syndrome (MFS), which displays variable manifestations in the skeletal, cardiovascular and ocular systems." (PMID 26630129, 2015). "Abnormal activation of TGFβ signaling was found to contribute to several features of the Marfan syndrome (MFS), a dominantly inherited disorder caused by mutations in the gene for fibrillin-1 (FBN1)." (PMID 26114882, 2015). "Although most mutations in fibrillin-1 (FBN1) cause Marfan syndrome (MFS), a microfibril disorder leading to transforming growth factor-β (TGFβ) dysregulation, domain-specific FBN1 mutations result in dominant GD." (PMID 25762570, 2015). "The Marfan syndrome (MFS), caused by mutations in the fibrillin-1 (FBN1) gene, has for example been successfully used as a model to study the complex pathophysiology of aneurysm formation in the thoracic aorta." (PMID 24587008, 2014). "Finally, one male with a PM also carried a mutation in the FBN1 gene, causing Marfan syndrome." (PMID 24987673, 2014). "In addition to identifying a novel mutation of FBN1 and broadening the spectrum of associated ocular phenotypes in Marfan syndrome, our findings suggest that pigmentary glaucoma may involve defects in fibrillin-1 microfibrils." (PMID 23444230, 2013). "This means that these variants in FBN1 gene alone could lead to the development of a thoracic aortic aneurysm, without a “true” mutation of the gene itself and the typical clinical features of Marfan Syndrome." (PMID 24453931, 2013). "A recent study reported a case of a person affected by DS who carried mutations in FBN1, the gene causative for a connective tissue disorder called Marfan Syndrome (MFS)." (PMID 23951402, 2013). "LDS shares many of its clinical features with Marfan syndrome (MFS), which is an autosomal dominant connective tissue disorder caused by mutations in the gene of fibrillin-1 (FBN-1)." (PMID 24086486, 2013). "Moreover, defective fibrillin-1 alters transforming growth factor-ß (TGF-ß) signaling, which in FBN1 deficient mice has been shown to account for manifestations of Marfan syndrome such as pulmonary emphysema, mitral valve prolapse, skeletal muscle myopathy and aortic root dilatation." (PMID 24349050, 2013). "For instance, mutations in exons 24–32 of FBN1 are usually associated with a severe form of Marfan syndrome (MFS), called neonatal MFS." (PMID 22539873, 2012). "For example, Marfan syndrome (MFS), which is caused by mutations in the gene encoding fibrillin-1, is characterized by increased fibrosis and impaired muscle regeneration." (PMID 22943509, 2012). "The importance of fibrillin-1 to the vasculature is demonstrated by autosomal dominant mutations in the fibrillin-1 gene known to cause Marfan Syndrome (MFS)." (PMID 24955633, 2012). "Screening of mutations in the fibrillin-1 (FBN1) gene in a Chinese family with autosomal dominant Marfan syndrome (MFS)." (PMID 22262941, 2012). "Marfan syndrome (MFS) is a dominant disorder, mainly caused by mutations in the fibrillin-1 gene (FBN1) located on chromosome 15q21.1." (PMID 22260333, 2012). "Fibrillin-1 mutations have clinically diverse consequences, since they can result in Marfan syndrome (MFS), an acromelic dysplasia named Weill-Marchesani syndrome (WMS), stiff skin syndrome (SSS) and isolated ectopia lentis." (PMID 20862248, 2010). "Since 1991 mutations in the fibrillin-1 (FBN1) gene have been found to be responsible for Marfan syndrome (MFS; MIM# 134797)." (PMID 20886638, 2010). "Mutations in FBN-1 are associated with various connective tissue disorders in humans including Marfan syndrome (MFS)." (PMID 19025617, 2008).
Marfan syndrome (continued). "Marfan syndrome (MFS) is a heritable connective tissue disorder caused by mutations in the fibrillin-1 gene." (PMID 17850668, 2007). "Marfan syndrome (MFS) is an autosomal dominant connective tissue disorder due to mutations in the fibrillin 1 gene." (PMID 17956619, 2007). "Because fibrillin-1 regulated activation of transforming growth factor β is impaired in Marfan's patients and fibrillin deficient mice, it is quite likely that accumulation of proteoglycans causing the prolapse of mitral valve, a prominent feature in Marfan's syndrome, is one of the consequences." (PMID 16611357, 2006). "Marfan syndrome (MFS), caused by mutations in the FBN1 gene, predisposes individuals to thoracic aortic aneurysm (TAA), a life-threatening complication." (PMID 41540272, 2026). "Marfan syndrome (MFS), caused by mutations in the Fbn1 gene, is associated with skeletal fragility; yet, the geometric and mechanical consequences for long bones remain underexplored." (PMID 42136730, 2026). "Such widespread distribution of fibrillin-1 is the result of the systemic nature of Marfan syndrome." (PMID 41541920, 2025). "Among them, 51 patients had genetically confirmed HTAD (Marfan syndrome (FBN1), Loeys-Dietz syndrome (TGFBR1, TGFBR2, SMAD3, TGFB2), vascular Ehlers-Danlos syndrome (COLSA1), and non-syndromic HTAD (ACTA2, MYH11, MYLK))." (PMID 41310758, 2025). "Marfan syndrome (MFS), caused by mutations in the fibrillin-1 gene (15q21), presents with abnormalities of the cardiovascular, ocular, and musculoskeletal systems." (PMID 40497939, 2025). "Marfan Syndrome (MS) is a connective tissue disorder, an autosomal dominant condition mostly caused by variants in the FBN1 gene, which encodes for fibrillin-1 protein." (PMID 40123664, 2025). "Marfan syndrome is a hereditary connective tissue disorder mostly due to mutations in the FBN1 gene, encoding fibrillin-1, a major component of the extracellular matrix." (PMID 41541920, 2025). "Initially, increased TGF-β was thought to drive AAA pathogenesis, based on mouse models of Marfan syndrome (MFS), where fibrillin 1 (FBN1) mutations led to enhanced activation of latent TGF-β." (PMID 40244390, 2025). "After exploring the phenotype patterns of Marfan syndrome and FBN1 rare LoF carriers, we applied PERADIGM to scan all genes in the UK Biobank 200K dataset to identify significant genes associated with Marfan syndrome-specific phenotypes." (PMID 41411243, 2025). "Marfan syndrome refers to an inherited connective tissue disorder in which skeletal integrity is affected by the FBN1 defects and is prone to osteoporosis and fragility fractures." (PMID 41541920, 2025). "This suggests that DNA demethylation of the promoter region successfully restored mRNA transcription levels in FBN1-heterozygous knockout cells of the same genotype as patients with Marfan syndrome." (PMID 40129967, 2025). "Mutations in fibrillin-1 (FBN1) cause various clinical conditions, such as Marfan syndrome (MFS)." (PMID 39939800, 2025). "A concern regarding the Fbn1+/Q2469X model is that late-stage saccular aneurysms differ from the fusiform morphology typically seen in Marfan syndrome, where the root and ascending aorta are most commonly affected." (PMID 41040364, 2025). "Marfan syndrome (MFS MIM#154700), due to pathogenic variants in the FBN1 gene, is an autosomal dominant connective tissue disorder, typically involving the skeletal, cardiovascular and ocular systems." (PMID 40176791, 2025). "Marfan syndrome (MFS) is an autosomal dominant genetic disorder caused by a mutation in the FBN-1 gene, which encodes the protein fibrillin-1, leading to connective tissue abnormalities." (PMID 40002744, 2025). "Causative genes include autosomal polycystic kidney disease (PKD1, PKD2), Ehlers–Danlos syndrome (COL3A1), Marfan syndrome (FBN1), Loeys–Dietz syndrome (TGFB2, TGFB3, TGFBR1, TGFBR2, SMAD2, SMAD3), and Majewski Osteodysplastic Primordial Dwarfism (PCNT)." (PMID 40004483, 2025).
Marfan syndrome (continued). "Marfan syndrome, the prototypical heritable aortopathy, results from pathogenic variants in FBN1, which encodes fibrillin-1, a critical ECM glycoprotein involved in microfibril assembly and sequestration of latent TGF-β complexes." (PMID 40981152, 2025). "Marfan syndrome (MFS), which is a dominantly inherited connective tissue disease resulting from a mutation in the FBN1 gene, exhibits variable manifestations affecting the cardiovascular, musculoskeletal, ophthalmologic, and pulmonary systems." (PMID 38728516, 2024). "The Marfan Syndrome (FBN1) database provides information about published DNA and protein variations affecting the FBN1 gene." (PMID 39434095, 2024). ": The Marfan Syndrome (FBN1) platform only provides structural context while CardioGraph, the TTN database, and CardioClassifier describes both contexts." (PMID 39434095, 2024). "The authors reason that increase in MFAP4 is a disease mechanism resulting from abnormal elastin formation in Marfan syndrome, instead of a direct result of altered FBN1 expression." (PMID 39830211, 2024). "Since fibrillin-1 defect is related to Marfan Syndrome, a human genetic disorder that severely impacts connective tissues, we detected if the fibrillin-1 interaction with elastin is also altered in the aortas of Marfan patients." (PMID 39120288, 2024). "P/LP variants in FBN1 (HGNC:3603, NM_000138.4) were identified in the 2 patients who also fulfilled the revised Ghent criteria for Marfan syndrome." (PMID 39669619, 2024). "Thoracic aortic aneurysm and dissection (TAAD) is a life-threatening condition associated with Marfan syndrome (MFS), a disease caused by fibrillin-1 gene mutations." (PMID 38177536, 2024). "This facilitates the interpretation of the amino acid change produced by the variation compared to the ACGV, and Marfan Syndrome (FBN1) platforms." (PMID 39434095, 2024). "Our study is relevant to human aorta pathology because the aorta of patients with Marfan Syndrome appears to exhibit similar disruption of fibrillin-1–elastin interactions." (PMID 39120288, 2024). "In the Russian Federation, very few genetic studies, such as an analysis of specific exons of genes ACTA2, NOTCH1, and FBN1 in patients with Marfan syndrome, have been performed on patients with thoracic aortic aneurysm." (PMID 39125885, 2024). "The overwhelming majority of FBN1 mutations cause Marfan syndrome, but variants in the TGFβ-binding-protein-like domain 5 (TB5) of FBN1 can result in Acromelic dysplasias." (PMID 38324186, 2024). "Marfan syndrome (MFS; MIM #154700) is a connective tissue disorder caused by pathogenic variants in the FBN1 gene, which encodes fibrillin-1, a key component of the extracellular matrix (ECM)." (PMID 39768188, 2024). ": CardioGraph, ACGV, and Marfan Syndrome (FBN1) are the only tools that provide information about the amino acid change produced by the variation." (PMID 39434095, 2024). "We found a novel SNV in FBN1 at the non‐canonical splice site c.443‐3C>G in a Chinese family with Marfan syndrome (MFS) spanning two generations." (PMID 39219382, 2024). "Marfan Syndrome (MFS) is the most common monogenetic autosomal-dominant disorder of connective tissue due to mutations in the gene encoding for fibrillin-1 (Fbn1) that presents with manifestations in many organs and systems in the body, resembling phenotypes of premature aging." (PMID 39959812, 2024). "FBN1 expression was increased in the CFB, supporting the fact that the lesions of Marfan syndrome caused by FBN1 are the heart valves and aorta." (PMID 38890483, 2024). "Marfan syndrome (MFS) is a connective tissue disorder caused by pathogenic mutations in FBN1." (PMID 39049903, 2024). "Thoracic aortic aneurysms and dissections are common in Marfan syndrome (MFS), a disorder resulting from Fibrillin-1 gene mutations." (PMID 38177536, 2024).
Marfan syndrome (continued). "The aim of this study from Spitalieri en co-workers was to uncover if impaired fibrillin-1 in Marfan syndrome is involved in dysregulated mechanosignalling." (PMID 39830211, 2024). "Marfan Syndrome (MFS) is an autosomal dominant connective tissue disorder affecting the fibrillin-1 gene." (PMID 39582980, 2024). "The other detected genes in this study, such as those related to Stickler syndrome (COL2A1 and COL11A1) or Marfan syndrome (FBN1), which have been proposed to modulate ocular growth through axial mechanism." (PMID 38243264, 2024). "More than 1,300 mutations in the FBN1 gene cause Marfan syndrome (MFS), a connective tissue disorder characterized by highly penetrant ascending thoracic aortic aneurysms (ATAAs) that progress to life-threatening aortic rupture and/or dissection in the absence of surgical intervention." (PMID 38545339, 2024). "There are six platforms that retrieve variation-specific information: ACGV, CardioGraph, CardioClassifier, Marfan Syndrome (FBN1), TTN database, and ARCV." (PMID 39434095, 2024). "Marfan syndrome (MFS) is a rare autosomal dominant inherited condition that affects connective tissue, caused by mutations in fibrillin-1 gene on chromosome 15." (PMID 38715046, 2024). "In individuals with Marfan Syndrome (MFS), fibrillin-1 gene (FBN1) mutations can lead to vascular wall weakening and dysfunction." (PMID 38461168, 2024). "Marfan syndrome (MFS) is a hereditary, autosomal dominant disorder due to mutations in the fibrillin-1 gene, that affects connective tissue in multiple organs, most notably the eyes, skeleton, and aorta." (PMID 38424531, 2024). "This variant is not present in gnomAD and is located in a highly conserved region of fibrillin-1, where other pathogenic genetic variants causing TAAD and Marfan syndrome have been documented before." (PMID 36346469, 2023). "Lumbar IVDs of patients with Marfan syndrome were significantly more degenerated, which indicated the crucial role of FBN1 in maintaining the homeostasis of IVDs." (PMID 36966180, 2023). "Fibrillin-1 (FBN1) is a significant factor in the pathogenesis of Marfan syndrome, a genetic disorder characterized by connective tissue abnormalities." (PMID 37784117, 2023). "Craniosynostosis is rare in FBN1-related Marfan syndrome but is reported in several cases in MFLS13,17." (PMID 37845262, 2023). "This has been most well developed in the mouse model of Marfan Syndrome induced via a C1039G substitution in the ECM gene Fibrillin-1 (Fbn1C1039G), which develops mitral valve disease." (PMID 37623368, 2023). "Microfibrils were first implicated in the formation and maintenance of elastic fibers because aortic tissue from patients with Marfan syndrome (MFS), caused by mutations in FBN1 and Fbn1 mutant mice showed aberrant elastic fibers." (PMID 37240210, 2023). "Marfan syndrome (MFS) is a systemic connective tissue disorder often caused by mutations of FBN1 (FBN1 gene, encoding fibrillin-1)." (PMID 37448791, 2023). "Marfan syndrome (MFS) is a rare inherited autosomic disorder, which encompasses a variety of systemic manifestations caused by mutations in the Fibrillin-1 encoding gene (FBN1)." (PMID 37443678, 2023). "The phenotype of Marfan syndrome (MFS) is defined by pleiotropic symptoms related to mutations in the FBN1 gene, which encodes the fibrillin-1 protein in physiological settings." (PMID 37159453, 2023). "Our study provided evidence for the involvement of FBN1 in the homeostasis of IVDs by demonstrating the fragility of IVDs in patients with Marfan syndrome." (PMID 36966180, 2023). "Further emphasising the importance of the ECM, Marfan syndrome, defined by mutations in the ECM component fibrillin-1 (FBN1), presents with an increased risk of aortic aneurysm." (PMID 37909406, 2023).
Marfan syndrome (continued). "The purpose of this study was to investigate the relationship between axial length (AL) growth and FBN1 genotype in patients with Marfan syndrome (MFS) after lens surgery and customize the selection of intraocular lens (IOL) power." (PMID 37477931, 2023). "In Marfan syndrome, the combination of excessive TGF-β synthesis and the uncontrolled release of TGF-β from FBN1 deficient ECM contributes to aortic destruction." (PMID 35307021, 2022). "Marfan syndrome (MFS), a monogenetic disorder, is caused by pathogenic variants of the fibrillin-1 gene FBN1." (PMID 34757469, 2022). "Mendelian disorders occurred more than once include Osteogenesis Imperfecta Type I (COL1A1, MIM:166200), Neurofibromatosis, Type I (NF1, MIM:162200) and Marfan Syndrome (FBN1, MIM:154700)." (PMID 35346302, 2022). "We observed partial hydroxylation of FBN1 N1088; the N1088I substitution in a <1-year-old patient diagnosed with a severe form of Marfan syndrome has been reported to have major effects on the cardiovascular system." (PMID 35700824, 2022). "Given its role in Marfan syndrome and its importance in elastin integrity, we assessed for levels of fibrillin-1 in the aorta." (PMID 36104385, 2022). "Marfan syndrome (MFS) is a genetic disorder of connective tissue that affects the fibrillin-1 protein (FBN-1)." (PMID 35082968, 2022). "Marfan syndrome (MFS), an inherited connective tissue disorder, is caused by a mutation in the FBN1 gene." (PMID 36505128, 2022). "The frequently observed molecular diagnoses (observed in more than one patient) include Osteogenesis Imperfecta Type I (COL1A1, MIM:166200), Neurofibromatosis, Type I (NF1, MIM:162200) and Marfan Syndrome (FBN1, MIM:154700)." (PMID 35346302, 2022). "The fibrillin-1 hypomorphic mice (mgR/mgR) are accepted as a model of Marfan syndrome and conducive to studying the clinical stages precursive to animal lethality." (PMID 35887698, 2022). "Marfan syndrome (MFS), caused by genetic mutations in the connective tissues such as mutations in FBN1 on chromosome 15 have been discovered in patients which can lead to many abnormalities that includes increased TGF-β1 causing irregularity in signaling." (PMID 36232782, 2022). "One of the representatives of fibrilinopathies is Marfan syndrome (MFS), caused by a mutation in the FBN1 gene located in chromosome 15, which encodes fibrillin-1." (PMID 35269536, 2022). "There are also ECM molecules that fulfill both structural and instructive roles, for example, the large cysteine-rich glycoprotein fibrillin-1, which is an obligatory component of elastic fibers and is the defective gene product in Marfan syndrome (MFS)." (PMID 35163812, 2022). "FBN1 is a gene with a well characterized role in the pathogenesis of thoracic aortic aneurysm (TAA) in the context of Marfan syndrome." (PMID 36277748, 2022). "In this category of patients, aortic dilatation andresulting complications develop from intrinsic molecular genetic alterations ofthe FBN1 gene in Marfan syndrome or the TGFBR1 orTGFBR2 genes in LDS." (PMID 39077175, 2022). "Marfan syndrome, an autosomal dominant disorder of connective tissue, is primarily caused by mutations in the fibrillin-1 (FBN1) gene, which encodes the protein fibrillin-1." (PMID 36035136, 2022). "Raman microspectroscopy previously detected changes in the Raman signatures of fibrillin-1 microfibrils and elastic fiber networks in the skin of healthy mice and a murine model of Marfan syndrome." (PMID 34095874, 2021). "Previous studies have evidenced the presence of genetic variants in FBN1 gene in isolated BAV patients with aortic root dilation and in Marfan syndrome patients with BAV." (PMID 34071740, 2021). "Marfan syndrome (MFS) is an autosomal dominant disorder of the connective tissue caused by mutations in the FBN1 (fibrillin-1) gene encoding a large glycoprotein in the extracellular matrix called fibrillin-1." (PMID 33709773, 2021).